RUNX3 (RUNX family transcription factor 3)
Diseases named in the same sentence as RUNX3 in open-access papers (continued):
Sharing a sentence is not in itself a finding about the gene and the disease.
psoriatic arthritis (2 papers, 2016 to 2018). Joint inflammation associated with psoriasis. "There is convincing evidence that RUNX3 is associated with AS and other forms of SpA, including psoriatic arthritis." (PMID 30687330, 2018). "Similar genetic associations at the RUNX3 locus have been also described in psoriatic arthritis, thereby revealing an unsurprising degree of genetic overlap between these two related forms of SpA." (PMID 30687330, 2018).
pulmonary fibrosis (2 papers, 2017 to 2025). Chronic progressive interstitial lung disorder characterized by the replacement of the lung tissue by connective tissue, leading to progressive dyspnea, respiratory failure, or right heart failure. "Conversely, inhibition of RUNX3 worsens irreversible pulmonary fibrosis induced by paraquat." (PMID 40356603, 2025). "RUNX3 may enhance the hydroxylation capacity of prolyl hydroxylase domain-containing protein 2 (PHD2), promote the degradation of hypoxia inducible factor-1α (HIF-1α), and weaken paraquat-induced EMT, thereby partially reversing pulmonary fibrosis." (PMID 40356603, 2025). "The mechanism may function through miR‐210‐mediated repression of RUNX3, which further decreases the hydroxylation activity of PHD2, enhances the stability of HIF‐1α, and promotes PQ‐induced EMT, aggravating the progression of pulmonary fibrosis." (PMID 28699703, 2017).
sarcoma (2 papers, 2022 to 2023). A usually aggressive malignant neoplasm of the soft tissue or bone. "Taken together, the role of Runx3 in the differentiation of mesenchymal sarcoma was limited compared with that of Runx2, although Runx3 knockout affected cell growth in vitro." (PMID 37212282, 2023). "Runx3 interacts with HEY1-NCOA2, and Runx3 knockout does not affect sarcoma phenotypes in vivo." (PMID 37212282, 2023).
scoliosis (2 papers, 2020 to 2025). A congenital or acquired spinal deformity characterized by lateral curvature of the spine. "In one study, removing runt related transcription factor 3 (Runx3), which disrupts neurons connecting spinal cord to proprioceptive mechanoreceptors, produced progressive scoliosis during the time of pubertal growth." (PMID 40888060, 2025). "Recently, we showed that Runx3 KO mice, which lack proprioceptive circuitry and Egr3 KO mice, in which muscle spindles fail to form whereas GTOs are retained, develop scoliosis." (PMID 32576830, 2020). "The observed difference in spine malalignment, namely C-shaped scoliosis exhibited by PValb-Cre;Piezo2f/f mice, as compared with an S-shaped scoliosis in Runx3 and Egr3 KO mice, indicates a variance in severity among genotypes." (PMID 32576830, 2020). "Interestingly, whereas PValb-Cre; Piezo2f/f spines exhibited a C-shaped scoliosis, i.e. one curvature, Runx3 and Egr3 KO mice exhibited an S-shaped, two-curvature scoliosis." (PMID 32576830, 2020).
Sepsis (2 papers, 2022 to 2025). Sepsis is defined as life-threatening organ dysfunction caused by a dysregulated host response to infection. "Likewise, when focusing on TFs related to the regulation of cytotoxicity genes (TBX21, EOMES, JUN, and RUNX3), alterations are evident within the sepsis cells." (PMID 41208955, 2025).
Sézary syndrome (2 papers, 2019 to 2022). "We examined regulation of RUNX3 by TOX in malignant CD4+ cells derived from PMBCs of Sézary syndrome patients." (PMID 31139323, 2019).
T-cell lymphoma (2 papers, 2021 to 2023). "The interaction between RUNX3 and c-MYC has previously been investigated in T-cell lymphoma." (PMID 35069677, 2021).
abdominal aortic aneurysm (1 paper, 2022). Enlargement and ballooning of the vessel that supplies arterial blood to the abdomen, pelvis and legs. "CD8 CTRAM and CD8 RUNX3 might have exerted opposite functions during the process of thoracic and abdominal aortic aneurysms because of the opposite trend on fraction alterations." (PMID 36703732, 2022).
adenoid cystic carcinoma (1 paper, 2025). A malignant tumor arising from the epithelial cells. "Loss of 1p36, a region containing the tumor suppressor gene RUNX3, was predominant in CCA consistent with various studies that revealed the deletion of this region in CCA, OSCC, and adenoid cystic carcinoma." (PMID 40354349, 2025).
anaplastic large cell lymphoma (1 paper, 2023). Anaplastic large cell lymphoma (ALCL) is a rare and aggressive peripheral T-cell non-Hodgkin lymphoma, belonging to the group of CD30-positive lymphoproliferative disorders, which affects lymph nodes and extranodal sites. "We and others demonstrated that RUNX3 is oncogenic and its overexpression is correlated with poor prognosis and drug resistance in NKTL and anaplastic large cell lymphoma (ALCL)." (PMID 37032358, 2023).
aortic aneurysm (1 paper, 2022). A ruptured aneurysm located in the wall of the proximal portion of the descending aorta proceeding from the arch of the aorta. "CD8 CRTAM cells exhibited an escalating trend of proportions both in TAA and AAA than their corresponding control samples, whereas CD8 RUNX3 cells exhibited an opposite trend, namely, decreased proportions in aortic aneurysm compared with the normal group." (PMID 36703732, 2022).
atransferrinemia (1 paper, 2021). Congenital atransferrinemia is a very rare hematologic disease caused by a transferrin (TF) deficiency and characterized by microcytic, hypochromic anemia (manifesting with pallor, fatigue and growth retardation) and iron overload, and that can be fatal if left untreated. "Our findings highlight possible role of Runx3 in human iron metabolism disorders, such as haemochromatosis, hemosiderosis and atransferrinemia." (PMID 34611951, 2021).
basal cell carcinoma of skin (1 paper, 2009). "Interestingly, it recently has been reported that RUNX3 overexpression was observed in basal cell carcinoma of skin." (PMID 19521519, 2009). "It recently has been shown that RUNX3 overexpression was observed in basal cell carcinoma of skin." (PMID 19521519, 2009). "Therefore, we thought that RUNX3 might have an oncogenic role in HNSCC as well as in basal cell carcinoma of skin." (PMID 19521519, 2009).
benign meningioma (1 paper, 2015). A grade I, slowly growing meningioma. "The most important finding of our current study was the methylation of RUNX3, which was found in more than half of atypical meningiomas [55.56 %] and also in a subset of benign meningiomas [16.67 %]." (PMID 25648363, 2015).
bronchioloalveolar carcinoma (1 paper, 2023). A well or moderately differentiated morphologic variant of lung adenocarcinoma characterized by tumor growth along the alveolar structures without stromal, vascular, or pleural invasion. "Similarly, RUNX3 is frequently inactivated in human atypical adenomatous hyperplasia (AAH) and bronchioloalveolar carcinoma (BAC), which correspond to mouse lung ADs, and inactivation of Runx3 induces lung ADs in mice." (PMID 36899846, 2023).
chronic gastritis (1 paper, 2005). Inflammation of the stomach that is chronic in nature. "Our previous study and others indicate that RUNX3 downregulation is frequently observed in chronic gastritis, intestinal metaplasia, and gastric adenoma in the GCI group, which are thought to be precancerous." (PMID 15685235, 2005). "In the remnant stomach mucosa, chronic gastritis and intestinal metaplasia were intensively observed with downregulation of RUNX3." (PMID 15685235, 2005).
chronic hepatitis C (1 paper, 2013). "In chronic hepatitis C patients, methylation frequencies in many TSGs, such as RASSF1, CDKN2A, APC, and RUNX3, were associated with shorter time-to-HCC occurrence." (PMID 24330717, 2013).
chronic kidney disease (1 paper, 2022). Impairment of the renal function secondary to chronic kidney damage persisting for three or more months. "We plan to continue collecting blood from patients with chronic kidney disease in subsequent studies to determine the specificity of RUNX3 and REG1A in the diagnosis of DKD." (PMID 35937821, 2022).
chronic myeloid leukemia (1 paper, 2022). "Previously linked to leukemogenesis, RUNX3 overexpression in BCR::ABL cells was shown to protect these cells from Imatinib-induced apoptosis, involving RUNX3 in chronic myeloid leukemia persistence." (PMID 35490198, 2022).
colon adenoma (1 paper, 2023). An adenoma that arises from the colon. "Biallelic inactivation of RUNX3 induced colon adenomas, which indicates a gatekeeper role for RUNX3 in colon adenoma development." (PMID 36766749, 2023).
emphysema (1 paper, 2023). "In contrast, the downregulated TFs (Mafb, Tead1, Irf8, and Runx3) had the lowest regulatory activity in module 4 of the PPE-induced emphysema model." (PMID 37816708, 2023).
endothelial dysfunction (1 paper, 2021). In vascular diseases, endothelial dysfunction is a systemic pathological state of the endothelium (the inner lining of blood vessels) and can be broadly defined as an imbalance between vasodilating and vasoconstricting substances produced by (or acting on) the endothelium. "Moreover, Runx3 holds the potential of aggravating endothelial dysfunction in DM." (PMID 34798872, 2021). "In conclusion, Cbl alleviates endothelial dysfunction by inactivation of the JAK2/STAT4 pathway and inhibition of Runx3 expression in DM." (PMID 34798872, 2021). "In conclusion, this study elucidates the mechanism that Cbl alleviates endothelial dysfunction in DM through inhibiting the JAK2/STAT4 pathway and Runx3 expression, providing novel insight into targeted therapy against DM and comprehensive understanding on DM progression." (PMID 34798872, 2021).
Ewing sarcoma (1 paper, 2021). A small round cell tumor that lacks morphologic, immunohistochemical, and electron microscopic evidence of neuroectodermal differentiation. "The regulatory network analysis sheds light on the Ewing Sarcoma regulatory behavior by identifying PAX7 and RUNX3 as promising master regulators for this cancer." (PMID 33924679, 2021).
folate deficiency (1 paper, 2019). A nutritional condition produced by a deficiency of FOLIC ACID in the diet. "Thirdly, genes with an opposite expression pattern in folate deficiency and repletion cell lines: SORBS2, DCN, SLFN11, RUNX3, GALC, and HSPB7." (PMID 30836646, 2019).
gastropathy (1 paper, 2020). "Runx3Δ and Cx3cr1-Runx3Δ mice older than 7 months typically showed exacerbated colon inflammation and 30% of them also developed gastropathy, resembling the phenotype of Runx3-/- mice." (PMID 32453801, 2020).
germinoma (1 paper, 2020). A malignant germ cell tumor arising in the central nervous system. "While this particular sample showed higher expression of GATA6, FOXA2, or HNF4A and hypermethylation of RASSF1, RUNX3, HIC1, or APC, its methylation pattern was partially common to that of germinomas or ECs." (PMID 32999426, 2020).
haemochromatosis (1 paper, 2021). "In this study, Runx3 KO mice showed a haemochromatosis‐like phenotype." (PMID 34611951, 2021).
Hip dysplasia (1 paper, 2020). The presence of developmental dysplasia of the hip. "We therefore examined whether these functions of Runx3 were associated with the hip dysplasia phenotype." (PMID 32576830, 2020). "Results showed severe, irregular type hip dysplasia in all Runx3 KO mice, which was manifested by a prominent cam over the femoral neck." (PMID 32576830, 2020).
HIV-1 infection (1 paper, 2014). The type species of lentivirus and the etiologic agent of acquired immunodeficiency syndrome (AIDS). "In order to determine the relevance of RUNX1 expression in HIV-1 infection in human patients we examined the expression of RUNX1, CBF-β and RUNX3 in primary T-cells." (PMID 24651404, 2014).
intrahepatic cholangiocarcinoma (1 paper, 2025). A carcinoma that arises from the intrahepatic bile duct epithelium in any site of the intrahepatic biliary tree. "Previous studies have reported that DNA copy number loss and promoter hypermethylation in this region lead to loss of RUNX3 expression in intrahepatic cholangiocarcinoma (iCCA), particularly in cases associated with liver fluke infection." (PMID 40354349, 2025).
latent infection (1 paper, 2023). "During latent infection of EBV, RUNX3 is a direct target of the viral transcription factor EBNA2 and the induced RUNX3 protein binds to the conserved RUNX binding site near the TSS of RUNX1 P1 promoter, leading to the repression of RUNX1." (PMID 37032358, 2023).
leukocytosis (1 paper, 2022). "A higher RUNX1 transcript level correlates with greater leukocytosis while RUNX3 expression is reduced in Philadelphia chromosome bearers." (PMID 36005134, 2022).
Listeria monocytogenes infections (1 paper, 2021). "Additionally, NCR3+ (natural cytotoxicity receptor) ILC3s have been shown to play a crucial role in both Salmonella and Listeria monocytogenes infections, in a Runt-related transcription factor 3 (Runx3)-dependent manner, modulating IFN-γ secretion." (PMID 33435303, 2021).
liver diseases (1 paper, 2025). "These differential methylation patterns suggest that RUNX3 methylation is dynamically associated with liver disease progression." (PMID 40559899, 2025). "To address this knowledge gap, we investigated RUNX3 methylation levels in a cohort exposed to both AFB1 and HBV, aiming to evaluate its potential as a sensitive biomarker for monitoring early liver disease caused by co-exposure to AFB1 and HBV." (PMID 40559899, 2025). "These indicated that during the progression of liver diseases, both AFB1 exposure and HBV infection could influence the methylation status of RUNX3." (PMID 40559899, 2025).
meningioma (1 paper, 2015). A generally slow growing tumor attached to the dura mater. "More importantly, according to Fisher’s exact test, RUNX3 methylation correlated with the presence of more aggressive, atypical meningiomas (p = 0.03)." (PMID 25648363, 2015). "RUNX3 methylation significantly correlated with meningioma WHO grade, therefore, can be considered as a potential indicator of tumor aggressiveness." (PMID 25648363, 2015). "In summary, this study provided evidence that p14ARF, RASSF1A, p15INK4B (CDKN2B), RUNX3, GATA6, p16INK4A (CDKN2A), NDRG2 and to lesser extent ATM and RARβ promoter methylation are associated with the development of meningiomas." (PMID 25648363, 2015). "RUNX3 methylation correlates with meningioma WHO grade and, therefore, can be used as a potential indicator of tumor aggressiveness." (PMID 25648363, 2015). "RUNX3 methylation was statistically correlated with higher grade meningiomas (p = 0.03), and RASSF1A was more frequently methylated in men than women (p = 0.04)." (PMID 25648363, 2015). "Thus, although the results of our present study require confirmation on larger patient cohorts, they suggest that RUNX3 methylation might be considered as the promising candidate biomarker for the assessment of meningioma aggressivenes." (PMID 25648363, 2015). "The aim of this study was to evaluate the methylation status of 12 cancer-related genes, namely ERCC1, hMLH1, ATM, CDKN2B (p15INK4B), p14ARF, CDKN2A (p16INK4A), RASSF1A, RUNX3, GATA6, NDRG2, PTEN, and RARβ, in 44 meningioma samples of WHO grade I and II." (PMID 25648363, 2015).
mesenchymal chondrosarcoma (1 paper, 2023). A morphologic variant of chondrosarcoma arising from bone and soft tissue. "Runx3, which is also expressed in mesenchymal chondrosarcoma and interacts with HEY1-NCOA2, replaced the DNA-binding property of Runx2 only in part." (PMID 37212282, 2023).
mesenchymal tumors (1 paper, 2020). "RUNX3, a runt-related transcription factor, is identified as a tumor suppressor gene in a wide variety of invasive and preinvasive epithelial and mesenchymal tumors." (PMID 33298014, 2020).
metastatic melanoma (1 paper, 2022). A melanoma that has spread from its primary site to another anatomic site. "Expression of RUNX3 can also promote monocyte-macrophage differentiation in metastatic melanoma." (PMID 35522574, 2022).
mismatch repair deficiency (1 paper, 2025). "Increased oxidative stress, inflammation-driven mismatch repair deficiency, and epigenetic alterations like RUNX3 and RASSF2 hypermethylation are implicated in carcinogenesis." (PMID 40364006, 2025).
myelodysplastic syndrome (1 paper, 2022). A clonal hematopoietic disorder characterized by dysplasia and ineffective hematopoiesis in one or more of the hematopoietic cell lines. "Recently, high RUNX3 expression was shown to be associated with poorer survival of patients with myelodysplastic syndrome (MDS)." (PMID 35490198, 2022).
myocarditis (1 paper, 2023). Myocarditis is a condition that is characterized by inflammation of the heart muscle (myocardium). "Notably, the accessibility of the chromatin regions overlapping with the ENCODE ChIP-seq peak of RUNX3 increased in the myocarditis state." (PMID 37264110, 2023). "Although RUNX2 and RUNX3 showed upregulation of their motif activities in myocarditis, their mRNA expression levels indicated minimal changes between the two time points, highlighting the importance of ATAC-seq for understanding the gene-modulatory network." (PMID 37264110, 2023). "RUNX3 was also highly enriched in NK and T cells during myocarditis in terms of motif activity, and increased accessibility of RUNX3 was confirmed across the whole genome." (PMID 37264110, 2023). "Thus, the TF RUNX3 showed the highest increase in activity during myocarditis." (PMID 37264110, 2023). "Since RUNX3 exhibits higher expression levels across all cell subpopulations than RUNX2, we propose RUNX3 as the primary TF upregulated during acute myocarditis." (PMID 37264110, 2023). "To find the major RUNX gene important in myocarditis pathogenesis, we compared the expression levels of RUNX2 and RUNX3." (PMID 37264110, 2023).
nasal polyps (1 paper, 2012). "More interestingly, two genes (RUNX3 and ARHGEF17) can function as tumor suppressor genes, and neither of these two genes has been previously investigated in the pathogenesis of nasal polyps." (PMID 23185289, 2012).
neurofibroma (1 paper, 2019). An intraneural or extraneural neoplasm arising from nerve tissues and neural sheaths. "To determine whether Runx3 affects Runx1 knockout SCPs, we used shRunx3 to transduce Runx1fl/fll;Nf1fl/fl;DhhCre DRG/tumor-derived mouse neurofibroma spheres." (PMID 31032403, 2019). "It is different from the Runx1 genetically conditional knockout, in which RUNX1 has no function but CBFB function is undisturbed, and the compensated Runx3 gene produces RUNX3 that can bind to CBFB to achieve RUNX transcriptional activities and contribute to neurofibroma formation." (PMID 31032403, 2019).
oropharyngeal cancer (1 paper, 2015). Carcinoma, predominantly squamous cell, arising from the epithelial cells of the oropharynx. "In this regard, frequent hypermethylation of the negative regulators of this pathway (DKK-3, RUNX3, SFRP1, SFRP2, SFRP4, SFRP5, and WIF1) was observed in oral and oropharyngeal cancers." (PMID 25487617, 2015).
salivary gland adenoid cystic carcinoma (1 paper, 2022). An adenoid cystic carcinoma arising from the salivary gland. "Nevertheless, the correlation of RUNX3 methylation and PNI was reported in salivary gland adenoid cystic carcinoma (ACC), indicating the necessity to analyze RUNX3 methylation in other types of neurotropic cancers." (PMID 35571032, 2022).
Salmonella Infections (1 paper, 2021). Infections with bacteria of the genus SALMONELLA. "Accordingly, genetic deletion of Runx3 in ILCs leads to high susceptibility of mice to Salmonella infection accompanied by decreased numbers of ILC1s and NCR+ILC3s." (PMID 34938670, 2021). "Moreover, Salmonella infection induces Runx3 expression in ILC1s and NCR+ILC3s, but not in NK cells." (PMID 34938670, 2021).